RUNX1 (RUNX family transcription factor 1)
Diseases named in the same sentence as RUNX1 in open-access papers (continued):
Sharing a sentence is not in itself a finding about the gene and the disease.
pancreatic cancer (17 papers, 2017 to 2024). "A same story occurs for RUNX1, so that its expression undergoes upregulation in pancreatic tumor cells associated with poor prognosis and high malignancy of pancreatic tumor cells." (PMID 32612456, 2020). "Another study on pancreatic cancer showed consistent results, with quantitative polymerase chain reaction results indicating that the mRNA level of RUNX1 was significantly higher in human pancreatic cancer samples than in normal pancreatic tissues." (PMID 38430423, 2024). "Pharmacological inhibition of RUNX1 can significantly suppress tumor growth in patient-derived organoids of primary pancreatic cancer." (PMID 38430423, 2024). "In a study of pancreatic cancer, the results of Kaplan–Meier survival analysis based on immunohistochemistry score data for RUNX1 suggested that a high expression level of RUNX1 is associated with a shorter OS time." (PMID 38430423, 2024). "The proapoptotic protein NOXA expression drives synthetic lethality to RUNX1 inhibition in pancreatic cancer." (PMID 38057816, 2023). "In pancreatic cancer, RUNX1 expression is upregulated and negatively correlated with patient prognosis." (PMID 36090038, 2022). "In contrast, we further examined the role of RUNX1 by overexpression RUNX1 level using a pcDNA3.1-RUNX1 expression vector, in two pancreatic tumor cells." (PMID 29245924, 2017). "Our study also identified that increased RUNX1 level is responsible, at least in part, for the decreased level of miR-93, explaining the downregulation of miR-93 in pancreatic cancer tissues." (PMID 29245924, 2017). "RUNX1 directly regulated miR-93 through suppressing expression and function of miR-93, miR-93 functions as a suppress gene in pancreatic cancer and regulates its target such as HMGA2." (PMID 29245924, 2017). "The majority (26/39, 66.7%) of pancreatic cancers received scores of 2+ or above, while a minority (13/39, 33.3%) of the pancreatic cancers had low level of RUNX1 expression." (PMID 29245924, 2017). "Given these clinical links, we further investigated the biological effect of RUNX1 on pancreatic cancer invasion." (PMID 29245924, 2017). "In this analysis, 61.5% (24/39) of pancreatic cancer samples had at least a 1.5-fold increase in RUNX1 mRNA expression levels relative to normal samples (P=0.001)." (PMID 29245924, 2017). "The high expression levels of RUNX1 in skin squamous cell carcinoma, esophageal, lung, colon and pancreatic cancers indicate that RUNX1 may drive oncogenesis in various solid tumors." (PMID 36766749, 2023). "YTHDC1 inhibits the glycolytic process through the miR-30d/RUNX1 axis in pancreatic cancer cells." (PMID 37258572, 2023). "Moreover, YTHDC1 was also found to inhibit glycolysis in pancreatic cancer through the miR-30d/RUNX1 axis." (PMID 35974388, 2022). "Targeting RUNX1 can be a potential therapeutic strategy in pancreatic cancer." (PMID 29245924, 2017). "Taken together, these results indicate that RUNX1 may contribute to pancreatic cancer progression through regulating pancreatic cells migration and invasion." (PMID 29245924, 2017). "Interestingly, RUNX1 was more highly expressed in pancreatic tumors chips, but its expression in solid tumors is still unkown, especially in pancreatic adenocarcinoma (PDAC)." (PMID 29245924, 2017). "However, RUNX1 and miR-93 expression in pancreatic cancers and corresponding normal tissues was positive correlated (P=0.04)." (PMID 29245924, 2017). "Here, we demonstrated that RUNX1 can regulate miR-93 in pancreatic cancers." (PMID 29245924, 2017). "Interestingly, it seems that RUNX1 exerts its stimulatory impact on the migration and malignancy of pancreatic cancer cells by inhibition of miR-93 since the overexpression of miR-93 diminishes the migration and invasiveness of pancreatic cancer cells." (PMID 32612456, 2020).
pancreatic cancer (continued). "Together, these findings defined a novel potential axis activated by the upregulated RUNX1 leading to pancreatic cancer invasion that may help the design of future clinical studies for this devastating disease as well as other diseases with aberrant levels of RUNX1." (PMID 29245924, 2017). "However, the role RUNX1 played in the carcinogenesis or progression of pancreatic cancer is largely unknown." (PMID 29245924, 2017). "Transcription levels of RUNX1, RUNX2, and RUNX3 were all increased in most types of cancers, including breast, esophageal, head and neck, and pancreatic cancer." (PMID 34485309, 2021). "To confirm the role of ER stress as a likely mechanism for RUNX1 imparting GEM resistance, we then evaluated whether chemically targeting ER stress could reverse the response of pancreatic cancer cells to GEM." (PMID 37697370, 2023). "Interestingly, MEK and Runx1 inhibition impairs pancreatic tumor cell growth, suggesting that ERK/Runx1 signaling is involved in the anti-tumor effect of this Gal3 inhibitor." (PMID 32168866, 2020). "However, whether RUNX1 can diectly regulate the expression of HMGA2 in pancreatic cancer is still not clear, and we plan to testify this axis in the future in vivo." (PMID 29245924, 2017).
melanoma (16 papers, 2009 to 2025). A malignant, usually aggressive tumor composed of atypical, neoplastic melanocytes. "The transcription factor RUNX1 is mutated in 3.03% of melanoma patients, and so far, 43 mutations are described in the literature for cutaneous melanoma." (PMID 34673281, 2021). "For instance, in malignant melanoma cells, CASC2 associates with miR-18a and then upregulates RUNX1 expression, subsequently suppressing cell proliferation, migration and invasion." (PMID 31728180, 2019). "Notably, this variant site on RUNX1 was one of the few variant sites detected with a high localization probability and was reported in COSMIC as somatic in melanoma patient." (PMID 34673281, 2021). "Two exceptions to this may be the RUNX1 mutation in an individual with myelodysplastic disorder and the MC1R mutation in an individual with two melanomas." (PMID 26257771, 2015). "Additionally, CASC2 may inhibit the development of malignant melanoma by regulating miR-18a-5p/RUNX1 axis." (PMID 38792557, 2024). "In addition, altered expression of Runx1 has been reported for non-melanoma skin malignancies." (PMID 36077435, 2022). "For RUNX1 we could not prove a posttranscriptional regulation by miR-129-5p in BRAF associated melanoma (data not shown)." (PMID 34063443, 2021). "Gene set enrichment analysis (GSEA) of all DEGs demonstrated marked functional disparities between AS and control samples, particularly in targets of RUNX1 RUNX1T1 fusion erythrocyte, melanoma, β-IFN–treated bronchial epithelial cells, Class A1 rhodopsin-like receptors, and tumor rejection." (PMID 40894479, 2025).
myocardial infarction (15 papers, 2018 to 2025). Gross necrosis of the myocardium, as a result of interruption of the blood supply to the area, as in coronary thrombosis. "Evidence indicated an increase of the transcription factor RUNX1 under pathological conditions such as myocardial infarction and dilated cardiomyopathy, suggesting its pivotal regulatory role." (PMID 39726787, 2024). "It has been reported that expression of RUNX1 has been increased in myocardial hypoxia and myocardial infarction, accompanied interactions and co-localization with Brg1." (PMID 39726787, 2024). "Previous studies established that Runx1 overexpression drives cardiac dysfunction by affecting calcium homeostasis in cardiomyocytes after myocardial infarction." (PMID 37936072, 2023). "Recent experimental studies on the role of Runx1 in the adverse cardiac remodelling following myocardial infarction have attracted substantial attention of the cardiovascular field." (PMID 37936072, 2023). "In the cardiovascular research field, we searched the published microarray gene expression profile of myocardial infarction (GSE46395) and found that RUNX1 expression was upregulated in myocardial infarction." (PMID 37927796, 2023). "Specifically, these reports showed adverse cardiac effects, including suppressed calcium handling by RUNX1 after myocardial infarction, in line with our results." (PMID 35935618, 2022). "Both α-SMA and Runx1 were discovered originally as CM dedifferentiation markers in human patients suffered from myocardial infarction." (PMID 32850848, 2020). "Additionally, we have observed a downregulation of RUNX1, that has been identified as a key regulator of adverse cardiac remodeling following myocardial infarction." (PMID 33238643, 2020). "A positive role for Runx1 was also suggested by its upregulation in hearts treated with oncostatin M, which has been shown to protect the heart after acute myocardial infarction, as well as in hearts that overexpress Erbb2 and show enhanced myocardial proliferation and regeneration." (PMID 32341028, 2020). "Conditional Runx1 deficiency in mouse cardiomyocytes has been demonstrated to protect the mouse against the negative consequences of cardiac remodelling after myocardial infarction." (PMID 32341028, 2020). "However, more recently RUNX1 has been identified as a key regulator of adverse cardiac remodelling following myocardial infarction." (PMID 32154891, 2020). "Whilst myocardial remodelling substantially occurred in control mice following myocardial infarction, characterized by declination of systolic function, thinning of the ventricular wall, and dilation of the ventricular chamber, the same parameters were absent in Runx1-deficient mice." (PMID 37936072, 2023). "In conclusion, exosomes derived from circRNA_0002113 lacking MSCs could suppress myocardial infarction by sponging miR-188-3p to regulate RUNX1 nuclear translocation." (PMID 35127703, 2021).
rheumatoid arthritis (15 papers, 2011 to 2024). A chronic, systemic autoimmune disorder characterized by inflammation in the synovial membranes and articular surfaces. "SNPs in the RUNX1 locus have previously been associated with rheumatoid arthritis and other immune-related diseases, and colocalization analyses have suggested that the causal SNPs are also associated with eosinophil proportions in blood." (PMID 37425935, 2024). "The SLC22A4 gene was identified as a susceptibility gene for rheumatoid arthritis, and it was negatively regulated by RUNX1, a transcription factor which was also significantly associated with rheumatoid arthritis." (PMID 35154281, 2022). "For instance, single-nucleotide polymorphisms (rs734232) affecting the consensus-binding site for RUNX1, or Runx1 itself, are associated with susceptibility to rheumatoid arthritis and psoriasis, while Stat3 gene was identified as risk locus for Crohn's disease and MS." (PMID 32226427, 2020). "However, dysfunctional interaction of RUNX1 with its binding site due to nucleotide polymorphisms links psoriasis not only with rheumatoid arthritis but also with systemic lupus erythematosus." (PMID 31402919, 2019). "Moreover, RUNX1 has been implicated in rheumatoid arthritis, a disease negatively associated with SCZ and which hence might share susceptibility genes with SCZ." (PMID 36344995, 2022). "Moreover, a study has demonstrated that EGT has a positive effect on immune system diseases caused by abnormal RUNX1 expression such as rheumatoid arthritis (RA) and non-alcoholic fatty liver disease." (PMID 36838636, 2023). "Previously, the interaction between the rs9275596 and RUNX1-rs1542876 locus was revealed, previously reported to be related to rheumatoid arthritis, systemic lupus erythematosus, and psoriasis." (PMID 32244438, 2020). "Other loci containing alleles robustly associated with higher eosinophil count and increased risk of rheumatoid arthritis were COG6, SPRED2, RUNX1, and the highly pleiotropic ATXN2/SH2B3/BRAP region." (PMID 27863252, 2016). "Moreover, aberrant expression of runt-related transcription factor 1 (RUNX1) has been implicated in defective regulation of sodium-hydrogen antiporter 3 regulator 1 (SLC9A3R1) and N-acetyltransferase 9 (NAT9) in both psoriasis and rheumatoid arthritis." (PMID 31402919, 2019). "Interestingly, several studies have suggested that RUNX1 regulates the expression of another transporter, SLC22A4, in rheumatoid arthritis." (PMID 29759484, 2018).
autoimmune disease (14 papers, 2006 to 2025). A disorder resulting from loss of function or tissue destruction of an organ or multiple organs, arising from humoral or cellular immune responses of the individual to their own tissue constituents. "Several of the genes that we have identified as targets for RUNX1 regulation in B cells have been linked to autoimmune diseases using genome-wide association study analysis, functional studies in animal models, or direct analysis in patients." (PMID 34810221, 2021). "RUNX1 is a transcriptional regulator likely to be involved in hematopoesis, which has already independently been linked to risk of autoimmune disease." (PMID 23028375, 2012). "RUNX1 has previously been implicated in other autoimmune diseases, which prompted us to further validate this transcription factor - SNP association." (PMID 23028375, 2012). "Additionally, key genes such as IL2RA and CD247, linked with risk genes PTPN22, PTPN2, and RUNX1, are consistently implicated across multiple conditions, including RA, lupus erythematosus, B-cell lymphomas, and autoimmune diseases." (PMID 40839671, 2025). "Importantly, RUNX1 has been associated with several autoimmune disorders, including SLE." (PMID 38067106, 2023). "In addition to establishing a novel regulatory function for RUNX1 in B cell activation, our results suggest that changes to the expression and functioning of RUNX1 in B cells could have causal roles in human autoimmune disease." (PMID 34810221, 2021). "RUNX1 mutations are frequently observed in various immune disorders, such as primary immunodeficiencies and autoimmune diseases, underscoring the importance of RUNX1 in immune function." (PMID 39132148, 2024). "For example, multiple JAK inhibitors are approved for the treatment of autoimmune diseases as well as hematopoietic malignancies, and autoimmune diseases commonly present in both RUNX1-FPD and MDS patients." (PMID 37581927, 2023). "First, mutations in RUNX1 are by definition preleukemic in individuals with RUNX1-FPD, who have increased prevalence of autoimmune disease and likely a proinflammatory milieu." (PMID 37581927, 2023). "Thus, ETV6/RUNX1 expression contributes to increased B cell tolerance, which aggravates autoimmune disease." (PMID 26919255, 2016). "Last, IL-3 is upregulated during infection, autoimmune disease, allergies, and AML, and the chronic inflammatory conditions in germline RUNX1 disease may elevate basal IL-3 levels." (PMID 37581927, 2023).
endometrial cancer (14 papers, 2018 to 2025). Primary or metastatic malignant neoplasm involving the endometrium (mucous membrane that lines the endometrial cavity). "Notably, in renal carcinoma endometrial cancer, RUNX1 was reported to be associated with EMT 39,40." (PMID 32549768, 2020). "RUNX1 was also confirmed to be upregulated in endometrial cancer and related to myometrial invasion." (PMID 31592165, 2019). "An orthotopic mouse model of endometrial cancer demonstrated that RUNX1 promotes distant metastasis." (PMID 29391048, 2018). "c and d The expression of RUNX1 was positively correlated with the expression of HMGA2 in endometrial carcinoma tissue." (PMID 29391048, 2018). "The results indicated that RUNX1 promotes distant metastasis in endometrial carcinoma at least partially dependent on the regulation of MMP-2 and MMP-9 expression." (PMID 29391048, 2018). "However, the two other genes, RUNX1 and TIMP2, which are common in cervical, ovarian, and endometrial cancers, have 5% mutation for amplification and deletion." (PMID 31205821, 2019). "We retrieved and analysed the data from the TCGA dataset to determine the relationship between the protein levels of HMGA2 and RUNX1 in endometrial carcinoma, and the results indicated that the expression of RUNX1 was positively correlated with the expression of HMGA2." (PMID 29391048, 2018). "Moreover, the expression of RUNX1 was positively correlated with the expression of HMGA2 in endometrial carcinoma tissue." (PMID 29391048, 2018). "The transcription factor RUNX1 and cofactor CBFB form a complex that promotes EMT in renal carcinoma and is elevated upon EMT in endometrial cancer." (PMID 36551618, 2022). "The results of qRT-PCR and the TCGA dataset analysis showed that the expression level of RUNX1 was higher in endometrial carcinoma tissues than that in normal endometrial tissues." (PMID 29391048, 2018).
hepatocellular carcinoma (14 papers, 2016 to 2025). A malignant tumor that arises from hepatocytes. "Consistent with previous observations for RUNX1, a similar trend was observed in hepatocellular carcinoma cell lines." (PMID 39309442, 2024). "In hepatocellular carcinoma, RUNX1 induces tumor cell migration, invasion, and metastasis by activating the COL4A1/FAK/Src signaling axis." (PMID 38430423, 2024). "In hepatocellular carcinoma, elevated RUNX1 levels have been shown to upregulate COL4A1 expression, thereby activating the FAK-Src signaling pathway and promoting the proliferation, migration, and invasion of hepatocellular carcinoma cells." (PMID 38430423, 2024). "In hepatoma cells, RUNX1 can interact with FOXO3A to induce the transcription of BIM, a target gene of the TGF-β signaling pathway." (PMID 36429115, 2022). "RUNX1 is downregulated in the early stages in hepatocellular carcinoma, and our findings suggest a potential role of DNA methylation in its regulation." (PMID 33676569, 2021). "Then, we analyzed the CMs of PA treated hepatoma cells for angiogenic factors, potentially regulating RUNX1 expression, such as VEGF, PDGF-BB and TGF-β, well known for their proangiogenic and fibrogenic role." (PMID 31635436, 2019). "For example, the expression of RUNX1 in hepatocellular carcinoma tissues is much lower than that in adjacent normal tissues and adjacent cirrhotic tissues." (PMID 31592165, 2019). "The tumor suppressive function of RUNX1 was also observed in hepatocellular carcinoma, where increased expression of RUNX1 could suppress cell migration and proliferation." (PMID 36429115, 2022). "This is in concordance with the observation of a low RUNX1 nuclear expression in human (Hep3B) and mouse (AML12) hepatoma cell lines and a positive expression in the HSCs." (PMID 34445195, 2021). "Our data demonstrate that RUNX1, induced by VEGF released from PA treated hepatoma cells, is one of the key responsible factors enhancing angiogenic activity in ECs." (PMID 31635436, 2019). "In conclusion, RUNX1 expression is not induced in hepatoma cells by PA treatment, but in ECs, mainly through VEGF and TGF-β, released from hepatoma cells after PA treatment." (PMID 31635436, 2019). "Therefore, RUNX1 expression seems to be triggered by cellular oxidative stress, dietary factors and with regard to hepatic steatosis, this is mediated by VEGF and TGF-β, which were shown to be released from hepatoma cells after PA treatment." (PMID 31635436, 2019). "Although RUNX1 was not present in parenchymal liver cells, hepatocytes and cholangiocytes, we did find faint RUNX1 mRNA expression in Huh7 cells, which is in concordance with the observation of a low RUNX1 nuclear expression in other hepatoma cells such as human Hep3B and mouse AML12." (PMID 31635436, 2019).